NF1 (neurofibromin 1)
Diseases named in the same sentence as NF1 in open-access papers (continued):
Sharing a sentence is not in itself a finding about the gene and the disease.
leukemia (continued). "We carried out the first detailed population-based study of leukaemia and non-Hodgkin lymphoma (NHL) associated with NF-1 in order to estimate the risk and elucidate the relationship between these conditions." (PMID 7947106, 1994). "TPCV is not considered for patients with NF1, due to the underlying predisposition to leukaemia and the high risk of forming secondary leukaemia with the use of lomustine and procarbazine." (PMID 38299304, 2024). "JMML is a rare type of leukaemia with a higher incidence in children with NF1." (PMID 36684394, 2023). "Early-onset leukemia may result from the presence of the homozygous MLH1 gene, a member of the DNA MMR genes with a concomitant NF1 gene mutation." (PMID 34566848, 2021). "Overexpression of NF1-GRD (GAP Related Domain) has been shown previously to restore normal cell growth in NF1-/- cells as well as downregulate high levels of Ras-GTP in leukemia cells." (PMID 29212209, 2017). "Among 25 JMML/NF-1 cases, 10 exhibited an NF1 loss-of-function mutation at near-100% variant allelic frequency (VAF) in combination with uniparental disomy involving almost the entire 17q arm, suggesting single mitotic recombination as the leukemia-causing event." (PMID 34633564, 2021).
neuroblastoma (45 papers, 2011 to 2025). Neuroblastoma (NB) is the most common solid, extracranial childhood tumor. "Future studies will define the effects of MEK or IGF1R inhibition on the invasive and metastatic capacity of RAS- and NF1-mutated neuroblastoma models." (PMID 39001383, 2024). "We have already shown that homozygous NF1 inactivating mutations confer very aggressive growth properties in the zebrafish neuroblastoma model." (PMID 37183825, 2023). "This is in keeping with reports of loss of NF1 function causing relapse in neuroblastoma, and the contribution of NF1 mutations to ALK inhibitor resistance." (PMID 37414143, 2023). "Here, we show that RAS-MAPK pathway activation through RAS mutation, NF1 deletion or ALK mutation also has a destabilizing effect in neuroblastoma." (PMID 36895472, 2023). "Two patients with neuroblastoma harboring, respectively, an NF1 mutation and BRAF mutation were treated with trametinib." (PMID 35681754, 2022). "The mechanism by which NF1 loss abrogates ERK to RAF feedback in neuroblastoma cells harboring ALK mutations remains elusive, but this will not prevent a rapid translation of this collateral sensitivity into the clinic." (PMID 35689207, 2022). "Here, we analyzed ALK inhibitor resistance in neuroblastoma, and demonstrated that loss of NF1 or mutation of NRASQ61K can lead to ALK inhibitor resistance." (PMID 35689207, 2022). "Extending the concept of collateral sensitivities, we identified MEK inhibitor hypersensitivity as a new vulnerability after NF1 loss in ALK-mutated neuroblastoma cells." (PMID 35689207, 2022). "We identified MEK inhibitor sensitivity as a collateral sensitivity of ALK inhibitor resistance due to NF1 loss in ALK-mutated neuroblastoma cells." (PMID 35689207, 2022). "Coggins showed that the MEK inhibitor trametinib induces YAP nuclear translocation while reducing cytoplasmic YAP in RAS- or NF1-mutated neuroblastoma cell lines, suggesting resistance to MEK inhibitor therapy via YAP activation." (PMID 34572875, 2021). "Three embryonal tumours have a reported association with NF1: rhabdomyosarcoma, neuroblastoma and Wilms’ tumours." (PMID 30187267, 2018). "MAPK (MEK) has also previously been linked to MYCN-independent NF1-mediated RA resistance, and MEK inhibition combined with RA treatment was proposed as a potential strategy to treat NF1-deficient neuroblastomas." (PMID 28187790, 2017). "Hölzel and colleagues also reported a loss of neurofibromin expression in 8/25 neuroblastoma cell lines and that a further SNP analysis of 20 neuroblastoma cell lines detected 50% (10/20) with abnormal NF1 alleles." (PMID 28637487, 2017). "Somatic NF1 mutations in neuroblastomas have been correlated with reduced expression of neurofibromin and poor patient prognosis, whilst higher levels of expression are associated with longer progression-free survival." (PMID 28637487, 2017). "A large-scale RNAi screen revealed an association of NF1 loss in neuroblastoma cell lines with resistance to retinoic acid (RA) treatment which is used as targeted therapy in the treatment of neuroblastomas." (PMID 28637487, 2017). "More recently, the role of nf1 mutations, which are associated with a poor outcome in human neuroblastoma, was also analyzed in the zebrafish MYCN model." (PMID 28894696, 2017). "We show that nf1 deficiency in the fish leads to aberrant activation of RAS-MAPK signaling in MYCN-induced neuroblastoma, which promotes both tumor cell survival and proliferation, leading to marked acceleration of tumor onset and increased tumor penetrance." (PMID 27130733, 2016). "Loss of Nf1 has been shown to increase the penetrance of MYCN-induced neuroblastoma in MYCN transgenic mice, and for our studies in zebrafish we determined the extent to which loss of nf1 synergizes with overexpression of the MYCN oncogene in this disease." (PMID 27130733, 2016).
neuroblastoma (continued). "Over the 20-week course of this experiment, neuroblastoma developed in one of the 14 transgenic MYCN-positive zebrafish with wild-type nf1 alleles, consistent with the relatively low penetrance and late onset of these tumors in the wild-type background." (PMID 27130733, 2016). "Our zebrafish model of MYCN-driven neuroblastoma with nf1 loss is ideally suited for the rapid in vivo analysis of the effects of candidate small-molecule inhibitors selected for this purpose." (PMID 27130733, 2016). "Loss of nf1 led to the aberrant activation of RAS signaling in MYCN-induced neuroblastoma, promoting both tumor cell survival and proliferation." (PMID 27130733, 2016). "To evaluate the histopathology of neuroblastoma tumors derived from PSNS cells with loss of nf1, we focused on the genotypes with mutant nf1a alleles and wild-type nf1b alleles." (PMID 27130733, 2016). "In this study, we use a zebrafish model to demonstrate that NF1 loss can potentiate the tumorigenic effects of MYCN-overexpression in high-risk neuroblastoma." (PMID 27130733, 2016). "To gain insight into the cellular and molecular consequences of NF1 loss in neuroblastoma, we used transgenic zebrafish models of neuroblastoma that overexpresses human MYCN in the PSNS." (PMID 27130733, 2016). "It was recently reported that knockdown of NF1 expression renders a neuroblastoma cell line resistant to retinoic acid-induced differentiation, and that NF1 deficient neuroblastoma tumors have a poor outcome." (PMID 21949657, 2011). "Moreover, human neuroblastomas recurrently developed de novo loss of NF1 and activating RAS mutations after ALKi treatment, leading to therapy resistance." (PMID 35689207, 2022). "Intriguingly, NF1 loss rendered neuroblastoma cells hypersensitive to MEK inhibition." (PMID 35689207, 2022). "However, inhibition of MEK signalling downstream of NF1 restores responsiveness to RA, suggesting a potential therapeutic strategy to overcome RA resistance in NF1-deficient neuroblastomas." (PMID 28637487, 2017). "Because of the very high penetrance and rapid onset of neuroblastoma in our nf1-deficient, MYCN-transgenic zebrafish model, it becomes one of a very few systems in which extensive analysis of the synergistic activity of two or more drugs can be evaluated in primary tumors in vivo." (PMID 27130733, 2016). "Furthermore, expression of the gene for the Ras GTPase-activating protein (RasGAP) NF1 is also associated with neuroblastoma patient outcomes, suggesting a more significant role for the RAS/MAPK pathway in neuroblastoma pathogenesis and disease relapse." (PMID 27014418, 2016). "However, a recent whole-genome sequencing study revealed that loss of NF1 is one of a strikingly high frequency of diverse mutations that hyperactivate the RAS-MAPK signaling pathway in relapsed neuroblastoma." (PMID 27130733, 2016). "Taking advantage of the optical transparency of our zebrafish neuroblastoma model, which allows us to monitor fluorescent tumor cell progression in vivo, we further investigated the compound effects of loss of nf1 and gain of MYCN on the kinetics of neuroblastoma progression." (PMID 27130733, 2016). "Taken together, these results suggest that MAPK signaling upon NF1 knockout in neuroblastoma cells harboring ALK mutations is associated with loss of negative ERK-RAF feedback, leading us to hypothesize that these cell lines may be particularly sensitive to MEK inhibitor treatment." (PMID 35689207, 2022). "• SHP099 significantly inhibited tumor cell proliferation in preclinical models.• Neuroblastoma cell lines, especially those with NF1 deletion or low expression, are highly sensitive to SHP099." (PMID 40115016, 2025). "We found that some neuroblastoma cell lines were resistant to single-agent MEK inhibition despite the presence of a RAS or NF1 alteration." (PMID 39001383, 2024). "In contrast, trametinib was potent in only two of the three NF1-altered neuroblastoma cell lines (right)." (PMID 39001383, 2024).
neuroblastoma (continued). "In this study, we assembled a panel of RAS- and NF1-altered neuroblastoma cell lines with variable IGF1R expression to evaluate the efficacy of the combination of a MEK inhibitor (trametinib) and an IGF1R inhibitor (ganitumab) in neuroblastoma." (PMID 39001383, 2024). "Four neuroblastoma cell lines were included based on the presence of the most common mutations affecting the RAS-MAPK pathway, RAS (KRAS in SJNB8 and NRAS in SKNAS), NF1 (SKNBE) and ALK (KCNR)." (PMID 36895472, 2023). "In line with our in vitro data, we detected de novo NF1 and NRAS or HRAS mutations in neuroblastomas from patients treated with the ALK inhibitors, ceritinib or lorlatinib, at resistance development." (PMID 35689207, 2022). "To formally demonstrate that loss of NF1 can cause ALK inhibitor resistance in neuroblastoma cell lines, we generated several neuroblastoma cell line models harboring NF1 knockouts." (PMID 35689207, 2022). "This presents a potential treatment option for patients with neuroblastomas that have lost NF1 and are resistant to ALK inhibitors, with the potential to impact clinical practice and future clinical trial design." (PMID 35689207, 2022). "Intriguingly, all neuroblastomas in patients treated with ceritinib acquired inactivating NF1 alterations, whereas neuroblastomas in patients treated with lorlatinib acquired activating RAS mutations." (PMID 35689207, 2022). "The RAS/MAPK pathway is frequently deregulated in many cancer types, including neuroblastoma, due to activating mutations in ALK/RAS/RAF or inhibitory NF1 mutations or deletions." (PMID 34572875, 2021). "Loss of NF1 activates RAS-MEK signalling, which in turn represses ZNF423, a critical transcriptional coactivator of the retinoic acid receptors; neuroblastomas with low levels of both NF1 and ZNF423 have an extremely poor outcome." (PMID 28637487, 2017). "It was a quarter of a century ago when NF1 was first reported to play a role in the development of neuroblastoma." (PMID 28637487, 2017). "Several NF1-deficient neuroblastoma cell lines exhibited only moderately elevated Ras−GTP levels, in contrast to NF1 tumour cells, indicating that neurofibromin can contribute differently to the negative regulation of RAS in different cell types." (PMID 28637487, 2017). "Genomic aberrations in NF1 were also found in primary neuroblastomas but at a lower frequency of 6% (5/83)." (PMID 28637487, 2017). "In vivo structure-function analysis with both the wild-type and inactive GRD domain of NF1 revealed that the GAP activity of the GRD domain is required for the tumor suppressor function of NF1 in neuroblastoma." (PMID 27130733, 2016). "This is consistent with our previous report in nf1 wild-type fish that MYCN-induced neuroblastoma tumors arise from adrenal sympathetic neuroblasts that are prevented from differentiation into chromaffin cells by the overexpression of MYCN." (PMID 27130733, 2016). "As in many other pediatric cancers, resequencing studies have documented a very low frequency of somatic mutations in neuroblastoma, including ALK (~9.2% of cases), PTPN11 (~2.9%), ATRX (~2.5%) and NF1 (~1%)." (PMID 27130733, 2016). "We have also shown that multiple neuroblastoma tumor cell lines were sensitive to treatment with the MEK inhibitor binimetinib, with sensitivity to MEK inhibition linked to NF1 protein expression and levels of phosphorylated MEK and ERK." (PMID 26925841, 2016). "These experiments show that NF1 uses different domains and signalling pathways to regulate the normal development of part of the nervous system and to prevent formation of neuroblastoma." (PMID 27130733, 2016). "Expression of the RAS-GTPase activating protein (GAP) protein NF1 is associated with activity of the RAS/MAPK pathway, and mutations in or deletions of the NF1 gene have been found in a number of cancers, including neuroblastoma." (PMID 26925841, 2016).
neuroblastoma (continued). "It was found that the frequency of mutations in the RAS-MAPK signaling pathway was significantly increased in relapsed neuroblastoma tumors, including mutations in ALK, NF1, BRAF, PTPN11, FGFR1, and the three RAS genes, and that the mutations in this pathway were mutually exclusive." (PMID 40115016, 2025). "Mutations in the RAS pathway occur frequently in neuroblastoma, not only in the RAS gene itself, but also through mutations in regulatory proteins and downstream signaling components (e.g., NF1 and PTPN11) or by triggering constitutive activation of the receptor kinases of the pathway (e.g., ALK)." (PMID 40115016, 2025). "Similar to neuroblastoma, ALDH1 expression has been reported in NF1-associated tumors." (PMID 39518076, 2024). "Moreover, SHP2 inhibition has recently been shown to reduce MAPK and mTOR signaling via inactivation of ERK, mTORC1, and S6K in neuroblastoma cells and tumors with low NF1 expression." (PMID 38032104, 2023). "In line with our results, an independent report suggested NF1 alterations were potentially involved in ALK resistance and a case report described a de novo NRASQ61K mutation upon development of ALK inhibitor resistance in a lorlatinib-treated neuroblastoma." (PMID 35689207, 2022). "Our study identifies NF1 loss and activating RAS mutations as bona fide clinically relevant causes of ALK inhibitor resistance in ALK-driven neuroblastoma and establishes reactivation of signaling downstream from the RAS-MAPK pathway as a mechanism of ALK inhibitor resistance." (PMID 35689207, 2022). "We recurrently detected NF1 loss-of-function mutations as well as activating mutations in RAS and its analogues in clinical samples from ALK inhibitor-resistant neuroblastomas and confirmed the causal contribution of these mutations to ALK inhibitor resistance in preclinical models." (PMID 35689207, 2022). "In addition, an association between inactivated NF1 and ZNF423 levels in neuroblastomas has been identified as a putative prognostic marker." (PMID 28637487, 2017). "Thus, even though neuroblastoma is a classical “developmental tumor”, NF1 relies on a very different mechanism to suppress malignant transformation than it does to modulate normal neural crest cell growth." (PMID 27130733, 2016). "Transgenic fish lines that expressed EGFP in the PSNS but not the MYCN transgene did not develop neuroblastoma, regardless of the mutational status of nf1, indicating that loss of up to three alleles of nf1 was insufficient to induce neuroblastoma on its own." (PMID 27130733, 2016). "To determine whether NF1 protein levels correlated with responses to binimetinib, we examined levels of NF1 protein in neuroblastoma cell lines." (PMID 26925841, 2016). "Here, we report that loss of the nf1a orthologue, which is much more highly expressed than nf1b during early PSNS development, greatly accelerates the onset of neuroblastoma induced by MYCN overexpression, with nearly complete penetrance by 5 weeks of age in nf1-deficient zebrafish." (PMID 27130733, 2016). "By contrast, the wild-type GRD domain failed to rescue the hypertrophy of sympathoadrenal cells in nf1 mutant embryos, indicating that the role of NF1 in suppressing neuroblastoma tumorigenesis differs from the mechanism that prevents PSNS hyperplasia during normal development." (PMID 27130733, 2016). "Our results support those studies, in that the GRD domain expressed in the same zebrafish line that suppressed neuroblastoma pathogenesis failed to suppress sympathetic neuroblast overgrowth in nf1-deficient zebrafish embryos." (PMID 27130733, 2016).